UQCC4 (ubiquinol-cytochrome c reductase complex assembly factor 4)
Description:
Required for the assembly and stability of the mitochondrial ubiquinol-cytochrome c reductase complex (complex III (CIII) or cytochrome b-c1 complex), a multisubunit transmembrane complex that is part of the mitochondrial electron transport chain (ETC) which drives oxidative phosphorylation.
Synonyms: C16orf91; CCSMST1; gs103; URLC5
Tractability: Antibody: UniProt predicts a signal peptide or a membrane-spanning region.
Gene: Protein-coding gene on chromosome 16 (1,419,752 to 1,420,756, reverse strand). Ensembl gene ENSG00000174109.
Subcellular location: Mitochondrion inner membrane
Gene Ontology:
Molecular function: protein-membrane adaptor activity
Biological process: mitochondrial respiratory chain complex III assembly
Cellular component: mitochondrion; mitochondrial inner membrane
Genetic constraint (gnomAD): Loss-of-function variants: 4 observed, 3.12 expected, observed/expected ratio (o/e) 1.28, 90% interval 0.58 to 1.91. That is too few expected variants to judge how well the gene tolerates losing a copy. Missense variants: 204 observed, 186.64 expected, observed/expected ratio (o/e) 1.09, 90% interval 0.97 to 1.23. Synonymous variants: 95 observed, 75 expected, observed/expected ratio (o/e) 1.27, 90% interval 1.07 to 1.5.
Homologues: Orthologues: chimpanzee UQCC4 (99% identical), guinea pig UQCC4 (67% identical), mouse Uqcc4 (66% identical), rat Uqcc4 (64% identical), pig UQCC4 (61% identical), dog UQCC4 (55% identical), zebrafish uqcc4 (32% identical), tropical clawed frog uqcc4 (25% identical).
Diseases named in the same sentence as UQCC4 in open-access papers:
UQCC4 is named in the same sentence as 1 disease in open-access papers, as found by Europe PMC text mining. Sharing a sentence is not in itself a finding about the gene and the disease.
UQCC4 shares sentences with these, for which no sentence is quoted: mucolipidosis (1 paper).